BRCA2 (BRCA2 DNA repair associated)
Diseases named in the same sentence as BRCA2 in open-access papers (continued):
Sharing a sentence is not in itself a finding about the gene and the disease.
ovarian carcinoma (continued). "Due to their role in BRCA1/BRCA2 DNA repair pathway, the loss-of-function mutations of RAD51C, RAD51D, BRIP1, and BARD1 genes have been generally considered as ovarian cancer susceptibility genes." (PMID 31366178, 2019). "In this study we utilized only the sequencing strategy (of BRCA1 gene and exon 11 of BRCA2 gene) and families with histories of breast and/or ovarian cancer from different regions (Pacific, Caribbean, Coffee, Andean and Eastern) from Colombia." (PMID 31341521, 2019). "Familial cancers other than breast and ovarian cancer were also associated with mutations of the BRCA1 and BRCA2 genes." (PMID 30622657, 2019). "In around 18% of ovarian cancer patients, it is possible to identify germline mutations in BRCA1 and BRCA2, especially in those with high-grade serous carcinoma." (PMID 31130614, 2019). "Twelve families in our curated dataset reported family or personal history of breast or ovarian cancer, five of which had germline BRCA1/2 detected, and three probands had positive BRCA2 germline mutations." (PMID 31703574, 2019). "Germline BRCA1 and BRCA2 mutations are most common in high grade serous histologic type (high grade serous cancer – HGSC), the most frequent type of epithelial ovarian cancer, and appear in 16–39.2% of cases." (PMID 30940100, 2019). "Given that the SNP protective effect is for ovarian cancer, we also determined UNG mRNA expression in tissues of 17 prophylactic oophorectomies from BRCA1 and BRCA2 mutation carriers." (PMID 30747491, 2019). "This study showed a similar activity and a trend toward improvement with olaparib versus PLD in patients with relapsed ovarian cancer and BRCA1 or BRCA2 mutations." (PMID 30820349, 2019). "For BRCA1 or/and BRCA2 among patients with both Breast and Ovarian cancer, the pooled prevalence was 9% (95% CI: 0–25%)." (PMID 30898109, 2019). "In the case of well annotated variants associated with high probabilities of developing aggressive and often fatal cancers, such as BRCA1 and BRCA2 and hereditary breast and ovarian cancer, clinical decisions are fairly clear." (PMID 31760949, 2019). "In contrast to the frequencies reported in BRCA1, methylation of BRCA2 occurs in <1% of ovarian cancers." (PMID 31225507, 2019). "More than half (8/15; 53.3%) of our cases were mutation carriers of genes for Fanconi anemia, and among the genes, BRCA2 and PALB2 are known to be associated with other cancers, including breast and ovarian cancers." (PMID 30840646, 2019). "Genetic testing for disease-causing mutations in BRCA1, BRCA2, PALB2, and other BC susceptibility genes is strongly recommended for people with a BC and/or ovarian cancer family history." (PMID 30940775, 2019). "We screened BRCA1 and BRCA2 genes in 132 Italian patients with early onset or family history of breast and/or ovarian cancers." (PMID 31336956, 2019). "Little is known about the genetic predisposition to breast and ovarian cancer among the Chilean population, in particular genetic predisposition beyond BRCA1 and BRCA2 mutations." (PMID 31125277, 2019). "A recent prospective cohort study estimated the cumulative ovarian cancer risk to age 80 years as 44% (95% confidence interval [CI], 36–53%) for BRCA1 and 17% (95% CI, 11–25%) for BRCA2 mutation carriers." (PMID 31064392, 2019). "More than one-fifth of ovarian carcinomas (about 23%) have hereditary susceptibility and germline mutations of BRCA1 and BRCA2 tumor suppressor genes; in particular contribute to 65–85% of these cases." (PMID 31608277, 2019). "Breast and ovarian cancers related to BRCA1 and BRCA2 mutations tend to occur more often in younger ages than their nonhereditary counterparts." (PMID 30975222, 2019).
ovarian carcinoma (continued). "Monoallelic mutations in five FA genes (BRCA1, BRCA2, PALB2, RAD51C, BRIP1) have now been confirmed to predispose to breast or ovarian cancer while biallelic mutations in these genes cause FA3." (PMID 31467304, 2019). "The aim of this report is to describe results of BRCA1 and BRCA2 Next Generation Sequencing Analysis (NGS) analysis in 132 selected Italian patients with breast/ovarian cancer." (PMID 31336956, 2019). "A complete clinical level analysis of BRCA1 and BRCA2 in hereditary breast/ovarian cancer includes the study of LGRs." (PMID 31741787, 2019). "In 1990, risk reduction surgery for epithelial ovarian cancer began to be implemented in patients with mutations in BRCA1 and BRCA2." (PMID 31182132, 2019). "We examined sensitivity to gemcitabine in BRCA2-defective ovarian cancer cell line PE01 and its BRCA2-revertant PE01(C4-2)." (PMID 30941207, 2019). "Pathogenic germline mutations in BRCA1 and BRCA2 (BRCA1/2) account for the majority of hereditary breast and/or ovarian cancers worldwide." (PMID 31528241, 2019). "This is the largest series evaluating germline BRCA1 and BRCA2 with comprehensive gene analysis in a Brazilian population of ovarian cancer patients." (PMID 30606148, 2019). "In this regard, we have shown that single nucleotide polymorphisms (SNPs) in genes from the base excision repair (BER) pathway can modify breast or ovarian cancer susceptibility in BRCA1 and BRCA2 mutation carriers." (PMID 30747491, 2019). "This mutation is common in patients with ovarian cancer, in which the overall frequency of mutations in BRCA1/BRCA2 is 28%, which is mainly attributable to this founder effect." (PMID 31545835, 2019). "We also calculated the mean number of family members tested for every BRCA1 and BRCA2 identified ovarian cancer patient before and after the educational campaign." (PMID 29506471, 2018). "The estimated penetrance of ovarian cancer by age 70 years was 21.5% (95% CI: 10.4-37.0%) for BRCA1 mutation carriers and 7.3% for BRCA2 mutation carriers." (PMID 29861850, 2018). "Our study reports for the first time the genetic diversity of BRCA1and BRCA2 genes in tumors from Northeast Mexican ovarian cancer patients." (PMID 29997359, 2018). "The poly-ADP-ribose polymerase (PARP) inhibitor olaparib, a targeted therapeutic drug approved by the Food and Drug Administration, is used to treat ovarian cancer patients with BRCA1 and BRCA2 mutations." (PMID 30453999, 2018). "What role, if any, these genetic alterations in BRCA1 and BRCA2 played in acquired chemoresistance of recurrent ovarian cancer remains to be investigated." (PMID 29797793, 2018). "Additionally, pathogenic variants in BRCA1 and BRCA2, autosomal dominant cancer risk genes, both crucial in the process of homologous recombination DNA repair, increase risks to CM and uveal melanoma (UM), as well as several other cancer types including breast and ovarian cancer)." (PMID 29641532, 2018). "The first observations of a double mutation in the BRCA1 and BRCA2 genes was found in 1997 in a casistica of patients of Ashkenazi origin affected by breast and ovarian cancer carrying both the 185delAG in the BRCA1 and the 6174delT BRCA2 gene mutations." (PMID 29346284, 2018).
ovarian carcinoma (continued). "Regarding the spectrum of mutations along the genes, 40 out of 60 mutations detected in BRCA1 were located outside the ovarian cancer cluster region (OCCR), in contrast with the findings for BRCA2, in which 22 out of 36 were located inside the OCCR." (PMID 30103829, 2018). "The estimates of ovarian cancer penetrance by age 70 were 39% (95% CI: 34-45%) for BRCA1 mutation carriers and 17% (95% CI: 13- 21%) for BRCA2 mutation carriers." (PMID 29861850, 2018). "Of eighty four patients (84/95; 88.4%) with first and/or second-degree family history of breast and/or ovarian cancer; 22 (26.2%) had deleterious/suspected deleterious mutations in either BRCA1 (7; 8.3%) or BRCA2 (15; 17.9%)." (PMID 29409476, 2018). "There were 5712 women tested for a BRCA1 and BRCA2 mutation at the HCP between 2001 and 2014, 887 of which had previously received a diagnosis of ovarian cancer." (PMID 29506471, 2018). "PARP inhibitors have shown promising antitumor activity in patients with impaired HR repair and have been recently approved by the FDA for treatment of ovarian cancer patients carrying BRCA1 and BRCA2 mutations." (PMID 29545922, 2018). "Out of a pool of 367 breast/ovarian cancer families Sanger‐sequenced for BRCA1 and BRCA2 gene mutations, we selected a cohort of 20 BRCA1/2‐negative families to be subjected to the BROCA‐Cancer Risk Panel massive parallel sequencing." (PMID 29271107, 2018). "Approximately 10–15% of ovarian carcinomas (OC) are attributed to inherited susceptibility, the majority of which are due to mutations in BRCA1 or BRCA2 (BRCA1/2)." (PMID 29298688, 2018). "Recent studies have implicated a plethora of factors involved in the ovarian cancer cisplatin resistance, including BRCA1 and BRCA2 mutations." (PMID 30061175, 2018). "There are five major histologic subtypes of ovarian cancer and high grade serous cancer (the most common) is reported in 75–100% of BRCA1 and BRCA2 mutation carriers." (PMID 29506471, 2018). "BRCA 1 and BRCA2 account for 15–22% of all high-grade serous ovarian cancer cases and 9–24% of all epithelial ovarian cancer cases." (PMID 29466291, 2018). "In these BRCA carriers, the lifetime risk of ovarian cancer ranges from 40–60% for BRCA1 and 10–30% for BRCA2, respectively." (PMID 30424539, 2018). "There was also an increase in the number of carrier tests performed for each BRCA1 and BRCA2 index ovarian cancer patient." (PMID 29506471, 2018). "A recent study carried out on many ovarian cancer patients showed that 3.6% displayed germline BRCA1 mutations, 3.3% germline BRCA2 mutations and 2.9% germline RAD15C mutations." (PMID 29389895, 2018). "There was also an increase in the number of carrier tests performed for each positive BRCA1 and BRCA2 ovarian cancer patient." (PMID 29506471, 2018). "A Colombian study has reported 100 patients with ovarian cancer diagnosis and 15% of mutation detection—13% in BRCA1 and 2% in BRCA2—including an 11% accounting for a founder mutation." (PMID 30103829, 2018). "In BRCA1- and BRCA2-positive women with prophylactic salpingo-oophorectomy, the ovaries showed occult primary ovarian cancer in 6 and 2%, respectively." (PMID 29177593, 2018). "Mutations in BRCA1 and BRCA2 (BRCA1/2) genes are associated with an increased risk of breast and ovarian cancers in women." (PMID 29433453, 2018). "The number of ovarian cancer cases among BRCA2 carriers was too small to permit reasonable estimation of confidence intervals." (PMID 29861850, 2018). "Since their discovery, hundreds of mutations have been discovered in the BRCA genes that predispose the individual to an increased risk of breast and ovarian cancer, such as BRCA1.185delAG, BRCA1.5382insC and BRCA2.6174delT in Ashkenazi Jews." (PMID 30174725, 2018).
ovarian carcinoma (continued). "The C-terminal region of BRCA2 apparently necessary for PAF1 recruitment is often deleted in truncating mutations associated with breast and ovarian cancer, suggesting its functional significance in tumor suppression." (PMID 29386125, 2018). "It should be noted that the eMERGE project is only returning results from two genes that are associated with breast and/or ovarian cancer risk (BRCA1 and BRCA2)." (PMID 30011878, 2018). "In ovarian cancer, the hereditary factor, represented by mutations in BRCA1 or BRCA2, is a strong prognostic factor." (PMID 29445866, 2018). "A second major cancer gene for breast and ovarian cancer, BRCA2, was localized to the long arm of chromosome 13 in 1994 and cloned and sequenced in 1995." (PMID 30586411, 2018). "The current standard RRSO at age 35–40(BRCA1) or 40–45 (BRCA2) is highly effective in reducing ovarian cancer incidence." (PMID 30340058, 2018). "The results of this interesting study showed that cumulative risk of developing ovarian cancer by age 60 and 80 respectively, were 0.60 and 0.83 from BRCA1 and 0.33 and 0.72 for BRCA2 carriers." (PMID 29389895, 2018). "In the most recent prospective report, the cumulative risk of epithelial ovarian cancer to age 80 was 49% for BRCA1 and 21% for BRCA2 mutation carriers." (PMID 30572612, 2018). "Specifically, gene internal deletion and/or point mutations within the BRCA2 gene can restore reading frames of BRCA2 mutated stop codons in CAPAN-1 pancreatic and POE ovarian cancer cells." (PMID 29334356, 2018). "The mean number of family members tested for each BRCA1 and BRCA2 positive ovarian cancer patient increased after the educational campaign from 2.54 to 3.27 (p = 0.071), and the number of family members identified as BRCA positive also increased significantly." (PMID 29506471, 2018). "Germline mutations in BRCA1 and BRCA2 (BRCA1/2) are associated with increased risk of breast and ovarian cancer." (PMID 29861850, 2018). "One of the sisters, affected with serous high grade ovarian carcinoma, had BRCA testing performed on cancer tissue in another center, with detection of the BRCA2 variant c.7975A>G." (PMID 30254663, 2018). "The proportion of patients diagnosed with ovarian cancer and the germline mutation found in the project was 17% with the BRCA1 gene and 2% with the BRCA2 gene." (PMID 30517521, 2018). "It has been estimated that there are at least 40 proteins participating in this pathway, but it was the recognition that this included BRCA1 and BRCA2 that provided the stimulus to study this pathway in breast and ovarian cancer." (PMID 29925418, 2018). "While the number of family members tested for each BRCA1 or BRCA2 positive ovarian cancer patient increased following the educational campaign, the mean number of family members tested was 3.27 following the campaign." (PMID 29506471, 2018). "Familial risk is associated with mutations in BRCA1 and BRCA2 genes, which conferred respectively 59% and 16.5% risk of developing ovarian cancer by the age of 70 in the Epidemiological Study of BRCA1 and BRCA2 mutation carriers (EMBRACE) in the UK." (PMID 30281663, 2018). "Our article uses the largest familial study of ovarian cancer to argue that there exists an ovarian cancer susceptibility gene on the X-chromosome acting independently of BRCA1 and BRCA2." (PMID 29447163, 2018). "We therefore knocked down PIN1 in BRCA2 null mammary epithelial cells and in a panel of BRCA1 and BRCA2 null ovarian cancer cells." (PMID 30590041, 2018). "Among the ovarian cancer patients, BRCA mutations were identified in 8.39% (13/155) of the patients, including 9 BRCA1 and 4 BRCA2." (PMID 29487695, 2018). "Forty out of 60 BRCA1 mutations were beyond the ovarian cancer cluster region (OCCR), in stark contrast with 22 out of 36 BRCA2 mutations being inside the OCCR." (PMID 30103829, 2018). "The cumulative risk for developing ovarian cancer is estimated to be 39% and 11% for BRCA1 and BRCA2 mutation carriers, respectively." (PMID 30174725, 2018).
ovarian carcinoma (continued). "The BRCA2 revertant ovarian cancer cell line, PEO4, showed a smaller but still significant (P = 0.001) 2-fold increase in RAD51 foci after cisplatin treatment." (PMID 29254481, 2017). "Olaparib and niraparib are both orally active PARP1 inhibitors that are effective in the treatment of ovarian cancers with BRCA1 and BRCA2 mutations." (PMID 28756516, 2017). "There is a significant effort to create small molecular inhibitors of RAD52 in order to clinically treat BRCA1 and BRCA2 mutant breast and ovarian cancers." (PMID 29145865, 2017). "Each of the most strongly associated PRSs displayed statistically significant interactions with age, with the exception of the ovarian cancer PRS in BRCA2 carriers, such that the hazard ratio per unit PRS decreased with increasing age." (PMID 28376175, 2017). "A meta-analysis investigating the ovarian cancer risk of 8139 patients with BRCA1 and BRCA2 mutations was published in 2003 and associated with the citation peak in 2004." (PMID 28086974, 2017). "An increased risk of breast or ovarian cancer is associated with monoallelic mutations in a subset of these genes (BRCA1, BRCA2, BRIP1, PALB2, RAD51C)." (PMID 28874143, 2017). "Together, BRCA1 and BRCA2 account for about 20 to 25% of cases of hereditary breast cancer and 15% of cases of ovarian cancer." (PMID 28651617, 2017). "As genetic testing becomes integrated into the routine management of individuals with ovarian cancer, more women with a germline BRCA1/BRCA2 mutation will be identified." (PMID 28780755, 2017). "Approximately 7000 new cases of ovarian cancer are diagnosed in the United Kingdom every year, of which 13% to 16% are caused by a germline mutation in either the BRCA1 or the BRCA2 (collectively termed “BRCA”) gene." (PMID 28407998, 2017). "Elevated PARP1 expression has been detected in several tumor types including breast and ovarian cancer with a further rise in triple-negative breast cancer and BRCA1- or BRCA2-mutated cancers." (PMID 29228718, 2017). "In our center, genetic testing of BRCA1 and BRCA2 is automatically offered to every woman with epithelial ovarian cancer diagnosed below age 70 years." (PMID 28780755, 2017). "In the present study, we have assessed the association between 320 SNPs associated with DAE and breast/ovarian cancer risk among BRCA1 and BRCA2 mutation carriers." (PMID 27796716, 2017). "It is now known that a significant proportion of the genetic risk of developing breast and ovarian cancer is due to germline mutations in the genes BRCA1 and BRCA2." (PMID 26574041, 2017). "Extensive research throughout the last few decades has revealed that mutations in BRCA1 and BRCA2, encoding essential proteins in the HDR pathway, are a critical component of HDR impairment in hereditary and sporadic breast and ovarian carcinomas." (PMID 28099152, 2017). "Other members of the FANCG complementation group include breast and ovarian cancer associated genes; FANCO (RAD51C), FANCS (BRCA1), BRCA2 (FANCD1), BRIP1 (FANCJ) and PALB2 (FANCN)." (PMID 28591191, 2017). "These inhibitors have been described as a powerful therapy for patients with hereditary breast or ovarian cancer containing mutations in the BRCA-1 and BRCA-2 genes that are essential for repairing DNA lesions by the homologous recombination pathway." (PMID 29073231, 2017). "Evidence of association with ovarian cancer risk (p < 10−2) was observed for six SNPs in BRCA1 mutation carriers and three SNPs in BRCA2 mutation carriers." (PMID 27796716, 2017). "These and subsequent studies propose EMSY amplification as a mechanism of BRCA2 pathway inactivation in sporadic breast and ovarian cancers." (PMID 28099152, 2017). "Recent literature suggests that up to 24% of ovarian cancers are associated with germline mutations, and of these, 29% have mutations in genes other than BRCA1 or BRCA2." (PMID 28250960, 2017).